NGF (nerve growth factor)
Diseases named in the same sentence as NGF in open-access papers (continued):
Sharing a sentence is not in itself a finding about the gene and the disease.
cognitive decline (43 papers, 2010 to 2025). "NGF signaling is essential for the survival of BFCNs, and loss of NGF signaling leading to cognitive decline is an early feature in AD and DS." (PMID 40514243, 2025). "Deficiencies in the TRKA/NGF axis are implicated in the depletion of cholinergic neurons and cognitive decline in AD." (PMID 40228177, 2025). "Recent research highlights the role of NGF in both aging and age-related conditions such as AD, where age-related disruptions in trophic signaling are linked to the cholinergic and cognitive decline characteristics of AD." (PMID 39595042, 2024). "Since the cholinergic system of the human brain is involved in memory function, and its loss is associated with cognitive decline, local NGF delivery directly to the cholinergic basal forebrain would be preferred." (PMID 30804738, 2019). "Delivery of neurotrophic factor genes such as nerve growth factor (NGF) to the brain have also shown some improvement of cognitive decline 13,14." (PMID 39990227, 2025). "Initially targeting cholinergic pathways in the basal forebrain, a 2001 small trial in eight patients of intraparenchymally injected fibroblasts expressing nerve growth factor (NGF) slowed cognitive decline and improved FDG PET measures." (PMID 40634156, 2025). "Considering the range of effects that neurotrophins such as BDNF and NGF have on neuronal function, their activity in the context of cognitive decline was analysed in vitro." (PMID 40807615, 2025). "Reduced NE turnover has also been linked to cognitive decline in stress and hypoxia studies with NE concentration regulating BDNF and NGF expression." (PMID 40546247, 2025). "The study also found that in the co-culture, BDNF and NGF levels increased after treatment with the test substances, suggesting the potential of the formulation in promoting neurogenesis and its utility in cognitive decline." (PMID 40807615, 2025). "Hippocampal NGF levels are decreased in the aged Ts65Dn brain and NGF retrograde transport is highly disrupted in degenerating BFCNs, correlating with cognitive decline." (PMID 35747206, 2022). "NGF/TrkA signaling also is attenuated in rodent models of aging, including cognitive decline via impairment of cholinergic function." (PMID 34138944, 2021). "AD-derived cognitive decline is closely related to alterations of neurotrophic factor levels, such as nerve growth factor (NGF) and brain-derived neurotrophic factor (BDNF), and changes in blood flow." (PMID 34138944, 2021). "Another study revealed the relationship between NGF decrease and cognitive decline in alcohol-dependent patients." (PMID 32231011, 2020). "A recent study reported that in the offspring of males exposed to alcohol during mating, the expression of NGF/BDNF was altered, potentially causing cognitive decline." (PMID 32231011, 2020). "This feature provides a direct administration of NGF into the lateral-ventricle-containing CSF to reach the cortical sites where the improved function of cholinergic neurons is essential to counter cognitive decline." (PMID 30804738, 2019). "Accumulating evidence indicates that NGF improves the survival of cholinergic neurons and reduces cognitive decline in humans with mild AD." (PMID 28441758, 2017). "NGF induced axonal sprouting toward the NGF, lowered the rate of cognitive decline, and increased cortical glucose uptake." (PMID 28473983, 2017). "Furthermore, a Phase 1 clinical trial also showed promising reversal of cognitive decline in human subjects using transplantation of NGF-secreting fibroblasts." (PMID 40710133, 2025). "Rescue of medial septal cholinergic neurons by NGF infusion has been shown to improve cognitive behavior after FPI, suggesting that loss of cholinergic basal forebrain neurons contributes to progressive cognitive decline following FPI." (PMID 37558465, 2023).
cognitive decline (continued). "Consistent with our in vivo data, the oral administration of Noopept has been shown to significantly increase the level of cleaved, mature forms of BDNF and NGF in the brain of wild-type rats, which have been used in aged humans to reduce age-related cognitive decline." (PMID 36614135, 2022). "NGF addition has been demonstrated to improve cognitive decline in AD." (PMID 34291567, 2021). "For example, longitudinal changes in TNFα, IL-8, and AD biomarkers in plasma along with a nerve growth factor (NGF) metabolism dysregulation could predict prospective cognitive decline in a population of DS individuals asymptomatic for AD." (PMID 34434101, 2021). "Previous studies show that cognitive decline in D-galactose-induced aging model mice is related to reduced nerve growth factor (NGF) protein levels and increased reactive oxygen species (ROS) in the brain, both of which cause degeneration of the hippocampal neurons and reduce neurogenesis." (PMID 34081627, 2021). "The results of this study support the argument that NGF signaling is altered in the aging brain and that such changes may contribute to age-related cognitive decline." (PMID 33804468, 2021). "The NGF pathway may also have potential as a biomarker of cognitive decline in AD, as its changes can predict future cognitive decline in patients with Down syndrome as they develop preclinical Alzheimer’s pathology." (PMID 30809111, 2019). "The further investigation of the NGF metabolic compromise in AD should provide clues as to how best re-establish an adequate trophic support for the phenotypic maintenance of BFCNs; the atrophy of which importantly contributes to cognitive decline in AD pathology." (PMID 34434101, 2021). "Importantly, longitudinal increases in 50 kDa proNGF levels in plasma over 1 year correlated to prospective cognitive decline over the subsequent 2 years, demonstrating a potential value of NGF-related biomarkers in identifying incipient cognitive decline in this population." (PMID 34434101, 2021). "The neural stem cells reversed the cognitive decline in animal models of the disease through secretion of BDNF and nerve growth factor (NGF)." (PMID 40710133, 2025). "Additional studies should be developed to uncover the mechanisms involved in NGF/P75NTR/TrkA and WNT/β-Catenin pathways disruption and the triggering of cell death and to confirm in vivo their involvement in cognitive decline." (PMID 39123618, 2024). "P38α has been reported to mediate WNT/β-Catenin and NGF/P75NTR/TrkA pathways disruption, selective BFCN death, and cognitive decline." (PMID 39123618, 2024). "In clinical studies, intracerebroventricular NGF administration in AD patients demonstrated an increase in the number of 11C-nicotine binding sites measured by PET and a reduced rate of cognitive decline." (PMID 21179413, 2010). "In the last few years, it has been proposed that a deficit of neurotrophic factors such as NGF and TGF-β1 can contribute to the pathogenesis of AD-related cognitive decline, and a strong neurobiological link exists in the AD brain between an early pro-inflammatory process and a deficit of TGF-β1." (PMID 38576478, 2024). "For example, EE and physical exercise increase neural plasticity, spatial and working memory, improve cognitive flexibility, increase hippocampal neurogenesis and expression of brain-derived neurotropic factor (BDNF) and nerve-growth factor (NGF), and even reverse cognitive decline." (PMID 38256537, 2024). "Another study in a phase I clinical trial focused on employing autologous fibroblasts transduced to express nerve growth factor (NGF) and could show positive evidence of a response to NGF through improved function of cholinergic neurons followed by improved cognitive decline after 22 months." (PMID 31480448, 2019). "In addition, we observed in the brain a decrease level of nerve growth factor (NGF), which has not been demonstrated previously in rodent models of surgery-induced cognitive decline." (PMID 32066806, 2020).
ischemia (43 papers, 2004 to 2025). A hypoperfusion of the BLOOD through an organ or tissue caused by a PATHOLOGIC CONSTRICTION or obstruction of its BLOOD VESSELS, or an absence of BLOOD CIRCULATION. "Therefore, it was necessary to give exogenous NGF to reduce the infarct size caused by ischemia and promote neuronal recovery and regeneration." (PMID 29423079, 2018). "Exosomes secreted by the transfected cells (NGF@ExoRVG) efficiently transported NGF mRNA and protein to the ischaemic region in a photothrombotic ischemia rat model." (PMID 38790015, 2024). "For example, co-transfection of RVG-Lamp2b and Nerve Growth Factor (NGF) plasmids was performed to efficiently deliver NGF mRNA with neuroprotective functions to EVs for the treatment of ischemia." (PMID 38543204, 2024). "As a result of increases in NGF and expression of NGF's TrkA receptor as well as ASIC3 in DRGs of ischemia limbs, our study further determined if NGF can affect the activities of ASIC currents at pH 6.7 with pre‐application of 100 ng/mL NGF for 24 h." (PMID 38312021, 2024). "Damaged myocardium produces high levels of nerve growth factor (NGF), a crucial trophic factor stimulating sympathetic axon outgrowth, within hours of ischemia–reperfusion." (PMID 37226390, 2023). "Further investigation of NGF-KO animals is crucial, especially considering NGF’s implication in multiple neurodegenerative injuries and diseases, such as traumatic brain injury, ischemia, and PD." (PMID 31105589, 2019). "Both brain-derived neurotrophic factor (BDNF) and nerve growth factor (NGF) have been reported to be neuroprotective in the middle cerebral artery occlusion (MCAO) rat model of ischemia." (PMID 30581534, 2018). "In ischemia reperfusion-injured rat model, TSG attenuated animal behavior changes and neurological function scores via increasing the expressions of NGF, growth-associated protein 43, and PKA catalytic subunit proteins." (PMID 29801454, 2018). "We detected mRNA expression of NGF in the LSG collected after ischemia, and the data indicated that A-803467 significantly attenuated the NGF expression." (PMID 28373696, 2017). "Borlongan and colleagues have shown that 3 days after intravenous administration of human umbilical cord-blood cells, there was an increased expression of BDNF, GDNF, and NGF in the rat brain after ischemia, compared to control animals." (PMID 26607630, 2016). "In the present study, we examined changes from the acute to the subacute stage of cerebral ischaemia and found that the expression of MK was upregulated early after ischaemia while that of NGF was upregulated later after cerebral ischaemia." (PMID 20726846, 2011). "Several immediate-early genes (c-fos, c-jun), growth factors (brain-derived neurotrophic factor, nerve growth factor), and heat shock protein 70 were overexpressed during early latent ischemia-tolerant state." (PMID 20298534, 2010). "To date, truncated forms of CRMP-2 have been identified in cultured neurons exposed to N-methyl-D-aspartic acid or depleted of nerve growth factor, in models of traumatic brain injury, ischemia, and sciatic nerve injury, and in the developing mouse brain." (PMID 20961402, 2010). "Lamina cribrosa cells and ONH astrocytes respond to conditions that mimic ONH ischemia by increasing NGF, BDNF and NT-3 protein expression and NGF secretion." (PMID 15579199, 2004). "Some studies reveal the promoting role of BDNF and NGF in the repair of nervous system injury by promoting the differentiation and regeneration of injured neurons and contributing to neuronal survival, growth, and apoptosis inhibition following ischemia." (PMID 40756569, 2025). "Importantly, the change in pro-BDNF level was found only in IVH, while the pro-NGF level was changed as well as in ischemia and asphyxia." (PMID 40003962, 2025). "Furthermore, salidroside elevated the mRNA expression and protein concentration of BDNF and NGF in ischemia periphery area, as well." (PMID 39090706, 2024).
ischemia (continued). "PI3K is able to be induced by neurotrophic factors (nerve growth factor, brain-derived neurotrophic factor, glial cell line-derived neurotrophic factor, and neurotransmitters, for instance), and the phosphorylation of Akt is also enhanced after ischemia." (PMID 36726841, 2023). "However, NGF upregulation in bladder ischemia appears to fail to protect neural structural integrity because ischemia was shown to downregulate the p75 NGF receptor expression prior to upregulating NGF expression." (PMID 34769293, 2021). "In response to ischemia, astrocytes produce multiple neurotrophic factors to protect neuron, including brain-derived neurotrophic factor, glia-derived neurotrophic factor; nerve growth factor, and vascular endothelia growth factor." (PMID 31167655, 2019). "In that study, NT-3 was found to upregulate expression of NGF by astrocytes in vitro, which indicates pericytes may boost NGF expression by astrocytes during ischemia or hypoperfusion in the injured neural tissue." (PMID 28524074, 2017). "The expression of nerve growth factor (NGF) and tyrosine kinase receptor A is rapidly upregulated following ischemia, promoting axonal sprouting and tissue repair." (PMID 35008440, 2021). "The present findings suggest that the increases in expression of MK, NGF and PECAM-1 induced by treadmill exercise after ischaemia are strongly related to such neuroprotective effects." (PMID 20726846, 2011). "In the process of NGF signaling, intracellular JNK and NF‐κB are found to be engaged in the effects of NGF on the activities of ASIC3 under the conditions of limb I/R injury and ischemia of PAD." (PMID 38312021, 2024). "Also in vivo, HA has been proved to persistently increase NGF, BDNF and TGF-β1 mRNA levels in cerebral cortex and hippocampus of mice injured with ischemia and reperfusion." (PMID 34526893, 2021). "However, as neuroprotective effects due to anti-oxidative properties were well described for other neurotrophic factors, e.g., the nerve growth factor, EGF probably also counteracts the ischemia-related oxidative stress." (PMID 28445478, 2017). "As results, C·H-astrocytes upregulated neurotrophic factors NGF and BDNF each 2.83 and 1.91 times those H-astrocytes, indicating C-Pc pre-treatment could contribute to recover the injury after ischemia and reperfusion." (PMID 26399322, 2015). "The findings further suggest that NGF is likely responsible for enhanced TRPV1, P2X3, and ASIC3 and plays a role in modulating the metaboreceptor component of the EPR in the hindlimb muscle ischemia." (PMID 22934005, 2012). "Neither trigger showed any effect on nerve growth factor expression, which in another study was found increased by PC with brief global ischemia in both early and delayed IT." (PMID 20298534, 2010). "The mechanisms, by which atypical antipsychotics may exert neuroprotection, include neurogenesis, protection against toxicity, ischemia, and insults or the upregulation of neurotrophic factors such as brain-derived neurotrophic factor (BDNF) and nerve growth factor (NGF)." (PMID 35887056, 2022). "Chlorogenic acid (and its metabolite dihydrocaffeic acid) administered either before or after ischemia reduced brain infarct volume, BBB damage and behavioral deficits in tMCAO rats by blunting MMP activation and increasing brain levels of EPO, HIF-1a and nerve growth factor (NGF)." (PMID 33383852, 2020). "In contrast, increased expression of Trk A in LC cells resulted in increased Trk A activation, implying NGF expression in these cells during ischemia may be self protective rather than protective toward RGCs." (PMID 15579199, 2004).
prostate carcinoma (41 papers, 1996 to 2025). A carcinoma that arises from epithelial cells of the prostate gland. "- NGF and its receptor TrkA are overexpressed in various types of cancer, including breast, ovarian, and prostate cancer.- Elevated NGF levels are associated with increased tumor growth, angiogenesis, and metastasis." (PMID 38375479, 2024). "The regulatory role of nerve growth factor (NGF) in prostate cancer was also found to be associated with the up-regulation of Nav1.7." (PMID 39060933, 2024). "TRAF4 was found to increase TrkA kinase activity through K27- and K29-linked ubiquitination upon nerve growth factor (NGF) stimulation, followed by the recruitment of downstream adaptor proteins and increased metastasis in prostate cancer." (PMID 35874839, 2022). "GSEA analyses from TCGA prostate cancer database confirmed that patients with higher NGF levels were positively associated with gene signatures associated with upregulated neuronal developmental-responsive signaling (KEGG, Gene Ontology, and Reactome)." (PMID 33398073, 2021). "Increasing evidence points to NGF and proNGF as diagnostic markers of both thyroid and prostate cancer." (PMID 28282920, 2017). "A possible biological rationale underlying the association between bone pain and prostate cancer survival outcomes may stem from the presence of growth factors within the prostate tumor, notably nerve growth factor (NGF)." (PMID 38980676, 2024). "Several PC-derived cell lines, representative of various degrees of malignancy, including LNCaP, DU145 and PC3 cells release abundant amounts of NGF, which might recruit prostate carcinoma-associated fibroblasts (CAFs) derived from human specimens." (PMID 36941697, 2023). "We further examined NGF expression with signatures reflecting AR signaling components in TCGA prostate cancer dataset and found that tissues expressing low levels of the NGF were significantly associated with gene signatures of upregulated androgen responsiveness by a GSEA." (PMID 33398073, 2021). "Glioblastoma, prostate cancer highly express NGF, which promotes angiogenesis through autocrine/paracrine secretion." (PMID 40860871, 2025). "We summarized the past and current literature on the interaction between nerves and cancer, with a special focus on pancreatic ductal adenocarcinoma (PDAC), prostate cancer (PCa), and the role of the nerve growth factor (NGF) in cancer." (PMID 38791953, 2024). "Regulation of several cancers, such as prostate cancer, a neurotropic cancer, is possible through neurotransmitters released by peripheral nerves and through NGF signaling." (PMID 39429264, 2024). "We utilized the impact of NGF on prostate cancer to emphasize the significance of NGF in cancer development." (PMID 39429264, 2024). "In the present study, we summarized the past and current literature on the history of the interaction between nerves and cancer, with a special focus on pancreatic ductal adenocarcinoma (PDAC), prostate cancer (PCa), and the role of the NGF in cancer." (PMID 38791953, 2024). "NGF has been shown in preclinical studies to mediate tumor nerve growth and has subsequently been targeted in clinical trials in prostate cancer via a small-molecule inhibitor of the NGF cognate receptor TRKA." (PMID 37719704, 2023). "Our previous evidence in quite different cell types, including primary neurons, PC12 cells and prostate cancer-derived LNCaP cells has shown a significant intersection between androgens and NGF in these cells." (PMID 36766714, 2023). "For instance, the precursor of nerve growth factor (proNGF) is overexpressed in prostate cancer and involved in the ability of prostate cancer cells to induce axonogenesis." (PMID 36105204, 2022). "The knockdown of the TrkA receptor suppresses the progression of liver cancer and a Trk receptor inhibitor antagonizes NGF-induced cell motility in prostate cancer." (PMID 34283074, 2021).